LGALS3 (galectin 3)
Diseases named in the same sentence as LGALS3 in open-access papers (continued):
Sharing a sentence is not in itself a finding about the gene and the disease.
adenoma (21 papers, 2004 to 2024). A neoplasm arising from the epithelium. "In the group of HTs associated to benign proliferating lesions, galectin-3 was expressed in two oncocytic adenomas." (PMID 15292926, 2004). "Nonetheless, galectin-3 has been identified as a key marker in assessing the aggressiveness of these adenomas, shedding light on their potential implications within the context of PCOS." (PMID 39958874, 2024). "The only marker which expression showed statistically significant difference between adenoma and carcinoma of Hurthle cells was Galectin 3 (p = 0.041)." (PMID 26503236, 2015). "One year after adrenalectomy, the plasma galectin-3 level had decreased significantly in the patients with aldosterone-producing adenoma." (PMID 25180794, 2014). "The sensitivity of the immunoexpression differences of these markers between adenomas and carcinomas is high ranging from 83.3% (Ret) to 85.2% (galectin-3 and CK19) to 87% (HBME-1)." (PMID 20181018, 2010). "Of the 46 adenomas, 19 (41.3%) were positive for galectin-3, 21 (45.6%) for Ret, 26 (56.5%) for HBME-1, and 23 (50%) for CK19." (PMID 20181018, 2010). "The inclusion of 11 participants receiving bromocriptine, while not confirming specific adenomas, contributes to understanding the association between hyperprolactinemia and galectin-3 levels in the context of IVF preparation." (PMID 39958874, 2024). "In this aspect, galectin-3 and PGP9.5 have both been shown to stain positive in the majority of parathyroid carcinomas while only expressed in few adenomas, and different panel combinations using galectin-3 and/or PGP9.5 with parafibromin have proven more reliable than using parafibromin alone." (PMID 33269427, 2021). "However, the specificity is only moderate for the distinction of adenomas from carcinoma by all markers ranging from 43.5% (HBME-1) to 58.7% (galectin-3)." (PMID 20181018, 2010). "In addition to WT1, we also found carcinoma-specific upregulation of LGALS3 (galectin-3) and UCHL1 (PGP9.5) (also upregulated in adenoma), which has been suggested as an IHC marker in parathyroid carcinoma." (PMID 37121965, 2023). "Parathyroid tumours were found to occur in 68% of Cdc73+/− mice, and 25% of these were adenomas and 75% were APAs (defined by having collagenous fibrous septa, and/or immunostaining for galectin-3 but lacking evidence of invasion or metastasis)." (PMID 28288139, 2017). "In their experience, >80% of SCAs lacked galectin-3 expression, and galectin-3 was uniformly present in hormonally active adenomas, including a case of Crooke cell adenoma, a rare and reportedly aggressive variant of corticotroph adenoma showing Crooke hyaline changes in >50% of neoplastic cells." (PMID 30020466, 2019). "The adenoma often stains positive for PFIB and APC and negative for galectin-3 (GAL-3) and PGP9.5, and its Ki-67 index is often <1%." (PMID 37834940, 2023).
Cognitive impairment (21 papers, 2019 to 2026). Abnormal cognition is characterized by deficits in thinking, reasoning, or remembering. "Galectin 3 was reported to promote Aβ oligomerization, associated with increased neuroinflammation and cognitive impairment; accordingly its knockdown produced opposite effects, compared to wild type animals, following hippocampal injection of Aβ." (PMID 37332353, 2023). "Our study explored the regulatory role of miRNAs on LGALS3 and their potential impact on cognitive impairment in T2DM patients." (PMID 39144658, 2024). "Modified citrus pectin (MCP) alleviated cognitive impairments and reduced neuroinflammation in Alzheimer’s-type dementia by inhibiting galectin-3." (PMID 39727960, 2024). "LGALS3 mediates Aβ deposition by regulating the activation of microglia and induces neuroinflammation and cognitive impairment in AD, and therefore is a key participant in AD pathophysiology." (PMID 36408104, 2022). "Our current research further expands our understanding of the involvement of galectin-3 in the field of cognitive impairment." (PMID 34900086, 2021). "Recent studies suggested that serum galectin-3 might be a potential biomarker for polycystic ovary syndrome, poststroke cognitive impairment and Idiopathic inflammatory myopathies complicated by interstitial lung disease." (PMID 37626284, 2023). "However, the relationship between galectin-3 and poststroke cognitive impairment (PSCI) remains ambiguous." (PMID 34900086, 2021).
diabetic nephropathy (21 papers, 2011 to 2025). "Changes of serum galectin-3 (Gal-3) is associated with the pathogenesis of diabetic nephropathy (DN)." (PMID 37291488, 2023). "A prospective study involving 1320 cases of T2D with an average follow-up of 9 years showed that the level of serum Galectin-3 was independently associated with the progression of diabetic nephropathy." (PMID 35083706, 2022). "The results showed that Rpph1 directly interacts with diabetic nephropathy-associated galectin-3 (Gal-3)." (PMID 34712322, 2021). "Galectin 1 is involved in vascular smooth muscle cell proliferation and Galectin 3 has been associated with diabetic nephropathy and atherogenesis." (PMID 21600003, 2011). "The results of a single-center prospective clinical study demonstrated that Galectin-3 levels are elevated in diabetic nephropathy and are positively correlated with the urine albumin/creatinine ratio." (PMID 35083706, 2022). "Because galectin-3 is related to tissue injury, our findings suggest a possible role of galectin-3 as an indicator of early diabetic nephropathy in patients with T2DM." (PMID 36175599, 2022). "The ratio of galectin-3-positive cells to the total number of macrophages in the tubules was also significantly increased in diabetic nephropathy." (PMID 27089335, 2016). "In renal disease, galectin-3 can play a role in the onset and development of diabetic and non-diabetic nephropathy." (PMID 27089335, 2016). "Moreover, there were significantly more galectin-3-positive cells in the glomeruli of diabetic nephropathy than in the glomeruli of other nephropathies." (PMID 27089335, 2016). "In animal models of diabetic nephropathy or ARF, galectin-3 has been shown to be upregulated." (PMID 27089335, 2016).
renal dysfunction (21 papers, 2012 to 2025). "High galectin-3 plasma levels are associated with increased risk of renal dysfunction [55•, 73, 74]." (PMID 36166185, 2022). "As an HF biomarker, Galectin-3 may have a diagnostic and prognostic role (prognostic in both acute and chronic HF), since its expression is upregulated, especially in severe HF patients and in those with renal dysfunction." (PMID 37298029, 2023). "Other biomarkers evaluated as predictors of adverse outcome are galectin-3, growth differentiation factor 15, mid-regional pro-adrenomedullin, and makers of renal dysfunction." (PMID 33852110, 2022). "It has been observed that circulating galectin-3 is increased in patients with renal dysfunction." (PMID 32893848, 2020). "They include hs-TnI/T and sST2, and to a lesser extent galectin-3, GDF-15 and some markers of renal dysfunction." (PMID 33852110, 2022). "In patients with hypertrophic cardiomyopathy or DCM, plasma galectin-3 increased only in those with renal dysfunction and a trans-cardiac galectin-3 gradient was not present." (PMID 29844319, 2018).
Arrhythmia (20 papers, 2014 to 2026). Any cardiac rhythm other than the normal sinus rhythm. "Galectin-3 is also a potential biomarker to predict arrhythmia risk or antiarrhythmic prophylaxis." (PMID 35191812, 2022). "Soluble ST2 and Galectin 3, biomarkers reflecting renal and cardiac fibrosis, could also be associated with an increased arrhythmia risk." (PMID 24982887, 2014). "“Culprit” biomarkers including soluble ST2 and Galectin 3, reflecting cardiac and renal fibrosis, could also be linked to an increased arrhythmia risk." (PMID 24982887, 2014). "In the multiple linear regression analysis, the CMR left ventricular ejection fraction and the number of arrhythmias were identified as two independent predictors of increased galectin-3 levels." (PMID 39451549, 2024). "The obtained concentrations of galectin-3 [ng/mL] were compared between the groups depending on the type of arrhythmia." (PMID 39451549, 2024). "Galectin-3 plasma concentrations predict arrhythmia recurrence following a single ablation procedure, whilst the data considering the value of galectin-3 in the anticipation of the effectiveness of the ablation are conflicting." (PMID 35410028, 2022). "The direction of research in children leads, as it does in adults, to the field of arrhythmias, where galectin-3 is researched for its ability to detect patients with a worse course of the disease and assumingly with poorer prognosis." (PMID 35410028, 2022). "Its plasma concentration predicts arrhythmia recurrence following a single ablation procedure, whilst the data are conflicting when considering the value of galectin-3 in the anticipation of the ablation effectiveness." (PMID 33801193, 2021). "The optimal point of arrhythmia burden for galectin-3 elevation was 6972 beats with a sensitivity of 73% and specificity of 71%." (PMID 33801193, 2021). "The arrhythmia number is a slightly stronger predictor of galectin-3 plasma level than the left ventricular ejection fraction." (PMID 33801193, 2021). "We analyzed ROC curves for arrhythmia burden to detect its cut-off value for increased galectin-3 plasma concentration." (PMID 33801193, 2021). "In the multiple linear regression analysis, the CMR left ventricular ejection fraction and arrhythmia number were independent predictors for galectin-3 elevation." (PMID 33801193, 2021). "During the research, hypotheses were formulated regarding the influence of galectin-3 on the ability to determine the type of cardiac arrhythmia and its progression, as well as other factors that were examined." (PMID 39451549, 2024). "Some limitations could also bias our results; e.g., stimulation of the cardiac beta-adrenoreceptors can affect the number and complexity of arrhythmia as well as galectin-3 plasma concentration." (PMID 33801193, 2021). "Over one-year follow-up, the patients with a lower both Galectin-3 levels (<15 ng/ml) and left atrium diameter (less than 40 mm) initially, had a 1-year better arrhythmia-free survival rate of 91%, after a single procedure and without administration of an arrhythmic drug." (PMID 29118378, 2017). "The results suggest that galectin-3 may not be a reliable diagnostic biomarker in the context of these specific types of arrhythmias, indicating a need for further research to identify other potential diagnostic markers for them." (PMID 39451549, 2024). "Based on the obtained results, it was confirmed that the occurrence of arrhythmia in the study group (all patients) is not related to the concentration of galectin-3 (p = 0.798)." (PMID 39451549, 2024). "On the contrary, all the otherbiomarkers (Galectin-3, Cathepsin-L and Caspase-3) demonstrated a significantdecline in all patients regardless of the arrhythmia outcome during long-termfollow-up." (PMID 39077532, 2023). "In our earlier study, we found that the concentration of aldosterone in patients with AF and MS is higher than in patients without arrhythmia, and the concentration of aldosterone positively correlates with galectin-3." (PMID 32784491, 2020).
Arrhythmia (continued). "The level of galectin-3 is not dependent on the type of arrhythmia VT and SVT." (PMID 39451549, 2024). "Additionally, the influence of gender on the level of galectin-3 was analyzed regardless of the type of arrhythmia (all patients)." (PMID 39451549, 2024). "At present, as a result of a larger study, the fact that galectin-3 in serum in patients with AF and MS is higher than in healthy subjects was confirmed, however, it was also found that this biomarker is higher in patients with AF and MS than in patients with MS without given arrhythmia." (PMID 32784491, 2020). "Galectin-3, PINP and PIIINP concentrations are higher in patients with AF and MS than in patients with AF without MS and MS without this arrhythmia." (PMID 32784491, 2020).
leukemia (20 papers, 2006 to 2025). A malignant (clonal) hematologic disorder, involving hematopoietic stem cells and characterized by the presence of primitive or atypical myeloid or lymphoid cells in the bone marrow and the blood. "After leukemia cells were stimulated for apoptosis by cisplatin, galectin-3 expression was upregulated and caused resistance to apoptosis in surviving cells." (PMID 24303084, 2013). "Moreover, the silencing of galectin-3 with RNAi increased the susceptibility of leukemia cells to apoptosis." (PMID 24303084, 2013). "This pathway is frequently dysregulated in leukemia and its activation through EVs-mediated Galectin-3 delivery further fortifies the leukemia cells’ resistance to treatment." (PMID 39572459, 2024). "The sustained activation of the NF-κB pathway in leukemia cells, triggered by EVs-mediated Galectin-3 transfer, thus plays a crucial role in their resistance to chemotherapy, making it more challenging to induce remission." (PMID 39572459, 2024). "We analyzed an RNA microarray gene expression data set of such samples (GSE110104) to determine if Lgals1 and Lgals3 are endogenously expressed in the mouse leukemia cells." (PMID 36430839, 2022). "There is increasing evidence that Galectin-1 and Galectin-3 are involved in the protective cross-communication between leukemia cells and the bone marrow microenvironment." (PMID 36430839, 2022). "Soluble galectin-3 is internalized by leukemia cells and transported to the nucleus, stimulates transcription of endogenous LGALS3 mRNA and thus activates the Wnt/β-catenin signaling pathway in leukemia cells, which is critical in cytotoxic drug resistance." (PMID 30237983, 2018). "Accordingly, treating human leukemia K562 cells with the chemotherapeutic agent cisplatin effectively increased galectin-3 expression." (PMID 26934444, 2016). "In the current study, we show that Galectin-3 protein levels are dynamically regulated and induced through a reciprocal communication between leukemia cells and protective stromal cells, and are further increased by chemotherapeutic drug treatment." (PMID 25869099, 2015). "Galectin-3 has been shown to engage the Wnt/β-catenin signaling pathway in leukemia cells." (PMID 39572459, 2024). "However, efficient leukemia migration and adhesion to stromal cells are significantly dependent on stromal galectin-3." (PMID 34830047, 2021). "Interestingly, there is a marked increase in galectin-3 mRNA in the same samples, suggesting that chemotherapeutic treatment of the BM, including leukemia cells and cells in the leukemia microenvironment, induces high amounts of galectin-3." (PMID 34830047, 2021). "Collectively, these findings indicate galectin-3 regulates BCP-ALL cell responses to chemotherapy through the interactions between leukemia cells and the stroma, and show that a combination of galectin-3 inhibition with conventional drugs can sensitize the leukemia cells to chemotherapy." (PMID 34830047, 2021). "Here, we have carefully analyzed the origins of Galectin-3 relevant to this type of leukemia." (PMID 25869099, 2015). "Inhibition of Galectin-1 or Galectin-3 activity is likely to be beneficial as a method to chemosensitize BCP-ALL cells and reduce or eliminate residual leukemia cells." (PMID 36430839, 2022). "Thus, the Galectin-1 and Galectin-3 that could protect BCP-ALL cells during drug treatment is complicated in terms of origin, and both leukemia cells as well as stromal cells are a possible source of these Galectins." (PMID 36430839, 2022). "To confirm that GM-CT-01 reduces binding of extracellular Galectin-3 to BCP-ALL cells, we harvested BCP-ALL cells from underneath the stroma and stained the leukemia cells for Galectin-3 with or without prior incubation with GM-CT-01." (PMID 36430839, 2022).
lymphoma (20 papers, 2006 to 2026). A malignant (clonal) proliferation of B- lymphocytes or T- lymphocytes which involves the lymph nodes, bone marrow and/or extranodal sites. "Intriguingly, aggressive lymphoma growth was markedly impaired in mice deficient in galectin-3, suggesting either that host galectin-3-mediated antilymphoma activity is required to sustain net tumor growth or that additional functions of galectin-3 drive key oncogenic mechanisms in NHL." (PMID 28157210, 2017). "However, high galectin-3 expression was found in the majority of DLBCL samples and cell lines, suggesting that galectin-3 may be associated with aggressive lymphoma subtypes." (PMID 23658855, 2010). "The expression of galectin-9 is far less extensive than that of galectin-1 and galectin-3 in lymphoma." (PMID 35677161, 2022). "Overall, research on the function of galectin-3 in lymphoma requires further exploration." (PMID 35677161, 2022). "Galectin-3 is widely expressed in stromal cells of adult T cells/lymphoma (ATLL)." (PMID 35677161, 2022). "Galectin-3-deficient M(IFN-γ/LPS) macrophages proved to be less effective than wild-type (WT) counterparts in antilymphoma activity, but were comparable to WT macrophages in the promotion of lymphoma growth stimulated by apoptotic tumor cells." (PMID 28157210, 2017). "Fabs were then tested for specific binding against the common lymphoma BCR antigens SAMD14/neurabin-I, LRPAP1, RpoC and galectin-3 using ELISA9,10,12,21,41." (PMID 38671086, 2024). "Therefore, galectin-3 may be used as an indicator of poor prognosis of lymphoma." (PMID 35677161, 2022). "Among a variety of lymphomas, anaplastic large-cell lymphoma (ALCL) neoplastic cells appear to be the only ones that consistently express galectin-3." (PMID 23658855, 2010). "One study demonstrated that galectin-3 was overexpressed in all cases of Ki-1+ ALCL and might be a potential marker of this lymphoma." (PMID 35677161, 2022). "Note that, in the WT animals, galectin-3 was expressed prominently by TAMs but not by lymphoma cells." (PMID 28157210, 2017). "Antilymphoma activity by M(IFN-γ/LPS) macrophages was mediated, in part, by galectin-3, a pleiotropic glycoprotein involved in apoptotic cell clearance that is strongly expressed by lymphoma TAMs but not lymphoma cells." (PMID 28157210, 2017). "Although galectin-3 is lowly expressed in normal lymphocytes and not detected in a number of lymphoma cell lines, its expression is markedly up-regulated in some lymphoma cell lines." (PMID 23658855, 2010). "Although galectin-3 was rationalized as a promising candidate molecular player in the modulation of macrophage activation by apoptotic cells and consequent promotion of lymphoma growth, we found that it had no part in this process, at least in our in vitro model." (PMID 28157210, 2017).